FOXP3 (forkhead box P3)
Diseases named in the same sentence as FOXP3 in open-access papers (continued):
Sharing a sentence is not in itself a finding about the gene and the disease.
periodontitis (27 papers, 2014 to 2025). An acute or chronic inflammatory process that affects the tissues that surround and support the teeth. "The hypermethylation of CpG sites in the Foxp3 locus caused by periodontitis may be responsible for its function impairment." (PMID 34177907, 2021). "During periodontitis, IL-6 has been associated with the detection of exFoxp3 Th17 cells, a population of Th17 cells that, at one point, expressed, but ultimately lost the Foxp3 expression." (PMID 33149125, 2020). "The inflammatory microenvironment in periodontitis compromises FOXP3+ Treg stability and function, thereby allowing unregulated immune responses that exacerbate periodontal tissue breakdown." (PMID 41399014, 2025). "Literature review pertaining to FOXP3+ regulatory T cells, Th17 cells, and periodontitis was analyzed." (PMID 41399014, 2025). "The FoxP3 mRNA and soluble IL-10 levels from the group with the T cells co-cultured with periodontitis BM-MSCs were drastically diminished to the extents even lower than the control T cells without BM-MSC co-culturing." (PMID 37490712, 2023). "As a result, the ratio of CD5+ T cells and FOXP3+ Tregs increased in the periodontitis pre-treatment group." (PMID 36329504, 2022). "Compared to healthy individuals, periodontitis patients have a decreased expression level of Treg cell-related gene Foxp3 and increased levels of Th17 cell-related genes RAR-related orphan receptor C (Rorc) and IL-17A." (PMID 35222410, 2022). "The percentage of Foxp3+ cells in the CD4+ gate was increased in animals with periodontitis compared to both baseline and RvE1-treated animals (both ≈70% difference, P<0.001)." (PMID 34012448, 2021). "In comparison to the CCUS lesions, CD3, CD4, CD8, mast cells, CD204 and FoxP3+ cell numbers in periodontitis lesions were significantly less, while the numbers of infiltrating CD20 and Mum1+ plasma cells were indistinguishable between these two lesions." (PMID 31923271, 2020). "Accordingly, we detected a higher frequency and increased the total number of CD4+Foxp3+ cells at day ten after the induction of periodontitis." (PMID 33149125, 2020). "The flow cytometry analysis of CD4+CD25+Foxp3+ cells in cervical lymph nodes and spleens of animals affected with experimental periodontitis revealed significant changes in the Foxp3 expression, Treg frequency, and Treg number." (PMID 33149125, 2020). "In the present study, the F4/80+, CD206+, and CD4+/Foxp3+ cells were monitored in the mice gingival tissue from the healthy (H), periodontitis (P), and cell injection (CI) groups." (PMID 33195441, 2020). "In active lesions in patients with periodontitis, Foxp3 mRNA was significantly overexpressed compared to inactive lesions, while TGF-β and IL-10 expression were downregulated in active periodontal lesions." (PMID 33149125, 2020). "In contrast, the frequency of Foxp3+ T cells was significantly decreased in the draining lymph nodes during periodontitis." (PMID 29453398, 2018). "CD25+ Foxp3+ Tregs are strikingly diminished in bone resorption lesions from periodontitis compared to healthy gingival tissues." (PMID 29805313, 2018). "However, FoxP3+ Tregs are diminished in bone resorption sites, highlighting the imbalance between protective and destructive immune responses in periodontitis." (PMID 41399014, 2025). "During periodontitis, Treg lymphocytes show a reduced Foxp3 expression and, instead, produce IL-17A and RANKL; thus, making the inflammatory milieu highly enriched in inflammatory cytokines like IL-6, pivotal in dictating Treg lymphocyte fate in periodontal lesions." (PMID 34220811, 2021). "Furthermore, an increased number of IL‐17A+ cells and decreased Foxp3+ cells per bone surface were observed in OVX/periodontitis rats and this skewed CD4+ T cell‐mediated osteoimmune response was rescued by the administration of probiotics." (PMID 34101283, 2021).
periodontitis (continued). "We detected a sharp reduction in the Foxp3 MFI on CD4+CD25+Foxp3+ cells after 5- and 10-days post-periodontitis induction at all cervical lymph-nodes (≈ 28% reduction) and spleens (≈ 17% reduction), although the effect was more significant in cervical lymph nodes." (PMID 33149125, 2020). "At least one study has demonstrated that antibiotic treatment that reduces levels of periodontal pathogens reduces the number of IL-17+ Foxp3+ T cells from peripheral blood of periodontitis patients, again supporting a connection between inflammatory environment, microbiome, and Treg plasticity." (PMID 32391008, 2020). "We analyzed the M2 macrophage and Foxp3 T cell populations during periodontitis." (PMID 33195441, 2020). "Interestingly, very few CD3, CD4, CD8, CD204, FoxP3+ and mast cells were identified in the periodontitis lesions." (PMID 31923271, 2020). "Tregs derived from mice with experimental periodontitis showed reduced Foxp3 expression, increased Th17-related gene expression, particularly IL-17A, and a reduced capacity to suppress osteoclastogenesis, thus indicating that periodontal inflammation affected Treg immunosuppressive capacity." (PMID 33149125, 2020). "Likewise, CD25+Foxp3+ Tregs were strikingly diminished in periodontitis lesions with bone resorption compared to healthy gingival tissues, and the correlation between RANKL and IL-10 was negative." (PMID 33149125, 2020). "Furthermore, a population of Foxp3+ IL-17+ cells has been identified in periodontal lesions of patients with periodontitis, indicating the possible conversion of Tregs to Th17 lymphocytes." (PMID 29805313, 2018). "Hence, therapies that boost FOXP3 expression or enhance the activity of co‐inhibitory receptors could provide effective means to manage the immune dysregulation seen in periodontitis." (PMID 41399014, 2025). "Also, at cervical lymph nodes, CD4+Foxp3+ cells were more frequent within the CD4+ compartment at day ten post-periodontitis induction (5% increase), although, at the same time point, the percentage of Foxp3+ cells within the CD4+CD25+ population was significantly reduced (50% less)." (PMID 33149125, 2020). "Increased pAKT1, pFOXO1, and FOXP3 along with decreased BIM proteins, were observed in gingival tissues from patients with chronic periodontitis compared with healthy controls." (PMID 40924302, 2025). "As documented before, when we analyzed the frequency of Foxp3+ cells among all CD4+ cells in cervical lymph nodes, the percentage increased in periodontitis as a feedback mechanism in the inflammatory process." (PMID 34012448, 2021). "As expected, there was an imbalance between the proliferation of effector T cells (CD4+CD25+Foxp3-) and Tregs (CD4+CD25+Foxp3+) during the experimental periodontitis." (PMID 34012448, 2021). "On the contrary, the frequency of Foxp3+ cells within the CD4+CD25+ compartment, which only includes activated T cells, was reduced during periodontitis, suggesting an imbalance between effector and regulatory T responses." (PMID 34012448, 2021). "Specifically, gingiva of RvD2-treated mice contained less CD4+ T-cells and Foxp3+CD4+ Treg cells, which are known to accumulate in the gingiva during inflammation and experimental periodontitis." (PMID 29922275, 2018). "In a murine model of periodontitis, Am80 reduced the percentage of CD4+ RORγt+ Th17 lymphocytes and increased the percentage of CD4+ Foxp3+ Tregs in the gingival tissues, cervical lymph nodes, and spleen." (PMID 29805313, 2018). "According to the fact that immune response to P.gingivalis in atherosclerotic patients is stronger than periodontitis patients, we believe the decrease of CD4+CD25+FOXP3+ T cells be related with the increased response towards P.gingivalis infection." (PMID 24466164, 2014). "Such negative feedback has also been found in periodontitis and FoxP3+ CD8+ T cells protect alveolar bone through reducing osteoclastogenesis and regulating the local immune response." (PMID 35222410, 2022).
periodontitis (continued). "To verify this possibility, we profiled FOXP3+ cells in gingival mucosa from both chronic and acute periodontitis non-HIV patients comparing them with healthy individuals." (PMID 34446704, 2021). "Interestingly, maximal expression of Treg-related genes Foxp3, IL-2, IL-10, CTLA-4, CD25, and GITR was reached later than Th17-related genes, on day 15 post-periodontitis induction." (PMID 33149125, 2020). "A small population of IL-17A+FOXP3+ cells were found in periodontitis, but not in gingivitis, suggesting the functional plasticity of Treg cells transforming into inflammatory Th17 cells in the periodontitis environment." (PMID 34177907, 2021). "Although we found increases in T helper type 17 (Th17) cells in periodontitis non-HIV patients 44, there were no significant changes in the frequency of FOXP3+ cells in their gingiva." (PMID 34446704, 2021). "The relatively high levels of Tregs (i.e. FoxP3+ T cells) in CCUS, did not vary between patient clinical severity scores, clinical periodontitis scores, histologic subtypes, gender, or CD3-/IL17+ cells." (PMID 31923271, 2020). "The presence or absence of periodontitis was assessed and the peripheral blood (PB) concentrations of IL-6, immunosuppressive cytokines (VEGF, TGF-β1, and CCL22) and proportion of T regulatory cells (Treg, CD3 + CD4 + CD25 + Foxp3 +) were measured." (PMID 35804048, 2022).
renal cell carcinoma (26 papers, 2008 to 2025). "On the other hand, renal cell carcinoma patients with strong infiltration of Foxp3+ lymphocytes had significantly higher CRP levels (elevated CRP with cut-off 5 mg/L)." (PMID 36980787, 2023). "The aim of our study was to clarify the role of FoxP3 in renal cell carcinoma (RCC) progression and metastasis." (PMID 37569676, 2023). "Despite these conflicting reports, a recent study has found that Foxp3 is expressed by macrophages infiltrating mouse renal cell carcinoma tumours." (PMID 27731341, 2016). "We previously reported that the expanded FoxP3+ Treg subset from peripheral blood of untreated renal cell carcinoma patients and also following IL-2 treatment co-express Helios." (PMID 26885615, 2016). "In the present study we confirmed a lack of expression of Foxp3 in normal macrophages, but we observed Foxp3 expression in macrophages infiltrating mouse renal cell carcinoma tumors." (PMID 25264896, 2014). "Somewhat higher FoxP3 expression was evident in TIL-derived γδTc from renal cell carcinoma, chromaffin tumor and especially gastric cancer, with the latter comprising 21% of expanded γδTc in the given example." (PMID 25477885, 2014). "Interestingly, in renal cell carcinoma higher CRP was associated with a stronger infiltration with CD8+, FoxP3+ and CD163+ cells and subsequently with worse prognosis." (PMID 31788452, 2019). "Furthermore, Vδ1Tc FoxP3 expression was greater than that of Vδ2Tc in expanded TILs from renal cell carcinoma." (PMID 25477885, 2014). "On the contrary, it has been reported that the clinical outcome was not dependent on the prevalence of Foxp3+ T regs in TILs in renal cell carcinoma." (PMID 18087278, 2008). "In A clinical study of 22 patients with renal cell carcinoma before and 3 months after cryoablation and blood samples of some patients, it was found that CD8+T, CD4+T, granzyme A(GZMA), CD11c transcription levels were significantly increased, and CD8/FOXP3 was increased after cryoablation." (PMID 36761748, 2023).
head and neck cancer (25 papers, 2009 to 2025). A primary or metastatic malignant neoplasm affecting the head and neck. "A higher CD8/FOXP3 ratio is associated with a more favorable prognosis for esophageal, rectal, and head/neck cancer." (PMID 35222387, 2022). "Accumulation of Foxp3+ Tregs in head and neck carcinomas (HNC) has been shown to have a favorable impact on patient prognosis." (PMID 39000453, 2024). "Contrary to the putative pro-tumorigenic effect, the presence of Foxp3+CD4+ T cells has been associated with a good prognosis in colorectal and head and neck cancers." (PMID 26604855, 2015). "This correlation between FoxP3+ Tregs and favorable clinical outcome has also been observed in oesophageal and head and neck cancers in our meta-analyses." (PMID 26462617, 2015). "For example in head and neck cancer tumor infiltrating lymphocytes are associated with better prognosis, especially CD3 and CD8 positive lymphocytes, as well as improved survival data for FoxP3 positive cell infiltrates." (PMID 34449004, 2022). "Thus, the role of FOXP3 Treg in head and neck cancer should be reinterpreted regarding the different context of subsites, respective treatment, and additional functional markers." (PMID 30153850, 2018). "In addition, we suggest another hypothesis that could explain the infiltration of FoxP3+ Tregs in head and neck cancers." (PMID 35805132, 2022). "In head and neck cancer, where tumors are exposed to several microbes, FOXP3 T cells were reported to be positively correlated with locoregional control and OS; this could be partially explained by the inhibition of harmful protumor inflammation by immunosuppressive Tregs." (PMID 30153850, 2018). "The existence of heterogenous anatomical sites and various treatments, including surgery with adjuvant RT/CCRT or primary CCRT +/− induction chemotherapy, in previous studies may explain the differential roles of FOXP3 in the clinical outcomes of head and neck cancer." (PMID 30153850, 2018). "Moreover, in head and neck cancer, FOXP3 may cooperate with the inflammation factor COX2 and with the migration/invasion factors AHNAK and cortactin to promote tumor progression." (PMID 26305693, 2015). "We studied the tumor samples of 280 head and neck cancer patients double stained for CD8+ and FoxP3+ T lymphocytes." (PMID 31546872, 2019). "Some studies suggested a negative prognostic value for high frequencies of tumor-infiltrating CD4+CD25+Foxp3+ Tregs in head and neck cancer, whereas others demonstrated a non-predictive or even positive prognostic role for these cells." (PMID 30658697, 2019). "This view fits with previous studies showing no or a positive prognostic effect of Foxp3+ Tregs in head and neck cancer, as here the number of co-infiltrating (activated) CD4+ and CD8+ T cells is also much higher than that of Tregs." (PMID 30658697, 2019). "By contrast, other studies have shown that FOXP3 expression does not influence the clinical outcome of head and neck cancers." (PMID 30153850, 2018). "Altogether, our analysis indicated that CD8, FoxP3, and CD68 immunoscore was a strong, independent, and significant prognostic marker that could be introduced into the landscape of current tools to improve the clinical management of head and neck cancer patients." (PMID 35805132, 2022).
liver cancer (25 papers, 2013 to 2025). An epithelial or non-epithelial malignant neoplasm that arises from the liver. "Furthermore, significantly higher Ki67 expression occurred on ChAT–GFP+Foxp3+ Treg cells and Chat–GFP+Foxp3– conventional T (Tconv) cells, suggesting that proliferation underlies the induction of ChAT-expressing T cells in liver cancer." (PMID 37640929, 2023). "Growth differentiation factor 15 (GDF15) facilitated tumor immunosuppression via interaction with CD48 on Treg cells and downregulation of E3 ligase STUB1, leading to accumulation of FOXP3 protein in liver cancer." (PMID 36733484, 2023). "An analysis of single-cell sequencing data of liver cancer immune cells found that lncRNA MIAT was significantly enriched in Foxp3+ CD4+ T cells, PDCD1+ CD8+ and GZMK+ CD8+ T cells, which mediated the immune escape of liver cancer." (PMID 36092924, 2022). "The high expression of tumor‐infiltrated LAYN+FOXP3+Helios+ Tregs, which possessed suppressive functions, was associated with tumor‐infiltrating exhausted CD8+ T cells and poor survival in liver cancer." (PMID 35474948, 2022). "The present study detected a large number of FOXP3-expressing cells in an overall much reduced NT compartment in liver cancer tissues." (PMID 26437631, 2015). "Similarly, high expression of tumor‐infiltrated LAYN+FOXP3+Helios+ Tregs, which possessed suppressive functions, was associated with tumor‐infiltrating exhausted CD8+ T cells and poor survival in liver cancer." (PMID 35474948, 2022). "On the other hand, FOXP3 may also influence liver cancer through other target genes, which are deserved to explore as well." (PMID 30378283, 2018). "In addition to the reduced cell number, a substantial fraction (22.76 ± 18.61%) of the CD3+CD56+ cells in liver cancer tissues acquired FOXP3 expression, a transcription factor critical for the development and function of conventional regulatory T cells." (PMID 26437631, 2015). "Remarkably, a similar enrichment for YY1, NRF1, E2F4, and FOXP3 TFs was also identified by GO-Elite in both the livers of miR-122 KO animals (GSE31453) and in the mouse model for liver cancer (GSE27713)." (PMID 37627157, 2023). "In this study, we would like to figure out the relationship and the mechanism of FOXP3, miR‐198, and MYC in liver cancer." (PMID 30378283, 2018). "Simultaneously, we observed a dysregulation in the expression of miR-187-5p in liver cancer cell lines, which may be attributed to transcriptional inhibition through the E2F1/FoxP3 axis." (PMID 37531206, 2023). "Licorice polysaccharide can inhibit H22 liver cancer proliferation by increasing the ratio of Th1 and Th2 cells through the activation of CD4+ and CD8+ T cells, decreasing the number of Treg cells, decreasing the expression of Foxp3, and increasing the Th1/Th2 ratio." (PMID 38792234, 2024). "In our CCR2/CCR4 double-K/O model, Foxp3+ Treg infiltration was reduced, while a meaningful infiltration of CD8+ T cells was observed in our CCR2/CCR4 double-K/O model, similar to what was obtained in a model of liver cancer following CCR2 K/O or neutralization." (PMID 35980743, 2022).